NOD2 (nucleotide binding oligomerization domain containing 2)
Diseases named in the same sentence as NOD2 in open-access papers (continued):
Sharing a sentence is not in itself a finding about the gene and the disease.
Crohn disease (continued). "Both NOD2 rs2066844 and rs2066845 polymorphisms have been associated to higher risk to Crohn’s disease and several types of cancer." (PMID 35123435, 2022). "Specific NOD2 polymorphisms within the leucine-rich repeat (LRR) domain have been linked to Crohn’s disease." (PMID 35625613, 2022). "The loss of NOD2 function resulting from these mutations enables bacterial invasion and an abnormal mucosal immune response is the underlying cause of Crohn’s disease." (PMID 36146565, 2022). "The NOD2/CARD15 gene is associated with chronic inflammatory conditions, such as Crohn’s disease, Blau syndrome, Yao syndrome and early-onset sarcoidosis." (PMID 35591901, 2022). "In some variants of Crohn’s disease, NOD2 lost this ability to induce autophagy upon MDP sensing and removing the intracellular bacteria." (PMID 34440800, 2021). "Mutations in NOD2 are frequently observed in patients with Crohn’s disease, an autoimmune disorder, suggesting the significance of the MDP–NOD2 pathway in activating immunity." (PMID 33920583, 2021). "Per 1000 Crohn’s disease patients, 214 cases would be expected to be NOD2 frameshift mutation carriers from the lowest PB risk group whereas only about 67 cases from the highest PB risk group would be expected to be carriers of the mutation." (PMID 34285202, 2021). "In 2001, two groups identified three common variants (p.Arg702Trp, p.Gly908Cys, and p.Leu1007ProfsTer2) in NOD2 that independently increased the risk of Crohn’s diseases." (PMID 32948841, 2021). "The NOD2 gene is also known as the major genetic risk factor for Crohn’s disease (CD) and Inflammatory bowel disease (IBD)." (PMID 34440800, 2021). "Meanwhile, a loss-of-function mutation in NOD2 is a widely accepted risk factor for Crohn’s disease in humans." (PMID 34573406, 2021). "We believe that the NOD2 variants determining the occurrence of Crohn’s disease came from common ancestors, resulting from mutual history." (PMID 34501225, 2021). "For example, the parasitic infection by Trichuris muris was reported to protect mice deficient in NOD2 (susceptibility gene for Crohn’s disease) from intestinal abnormalities." (PMID 34745091, 2021). "NOD-2 mutations have been associated with other chronic inflammatory illnesses such as Crohn’s disease and EOS." (PMID 34781959, 2021). "This analysis showed that NOD2 recessivity significantly and specifically associates with Crohn’s disease." (PMID 33692434, 2021). "NOD2 is particularly relevant for human pathologies as mutations in the NOD2 locus are linked with inflammatory genetic diseases such as Crohn’s disease, early onset sarcoidosis, and Blau syndrome." (PMID 33432113, 2021). "The first gene identified to be associated with Crohn’s disease was Nucleotide-binding oligomerization domain-containing protein 2 (NOD2)." (PMID 34692176, 2021). "Our results indicate more significant effects of homozygous and compound heterozygous NOD2 mutations than single NOD2 genetic variants in conditioning Crohn’s disease." (PMID 34501225, 2021). "Carriership of the NOD2 genetic risk for Crohn’s disease is associated with an increased relative abundance of Enterobacteriaceae." (PMID 34899756, 2021). "These include the most studied variants in susceptibility gene NOD2 (CARD15), which is associated with small bowel disease, stricturing disease and early surgery in Crohn’s disease (CD)." (PMID 34828659, 2021). "Loss-of-function mutations of NOD2 lead to susceptibility to an inflammatory bowel disease called Crohn’s disease." (PMID 33993194, 2021). "Collectively, our findings show that recessive inheritance of rare and low frequency deleterious NOD2 variants account for 7–10% of CD cases and implicate NOD2 as a Mendelian disease gene for early onset Crohn’s Disease." (PMID 33692434, 2021). "Intriguingly, our data demonstrate that Crohn’s disease‐associated mutation NOD2 1007fs which is unresponsive to MDP is still activated by S1P." (PMID 33942347, 2021).
Crohn disease (continued). "Curiously, the same NOD2 R702W mutation is one of the strongest known genetic risk factors for Crohn’s disease, suggesting a pivotal role for NOD2 in balancing host inflammatory responses." (PMID 34276708, 2021). "CARD15/NOD2 is the most significant genetic susceptibility in Crohn's disease (CD) even though a relationship between the different polymorphisms and clinical phenotype has not been described yet." (PMID 33708009, 2021). "Crohn’s disease‐associated mutation NOD2 1007fs results in a partial deletion in the LRR region and hence defective detection of MDP." (PMID 33942347, 2021). "NOD2 germline mutations are associated with Crohn disease and early onset sarcoidosis or Blau syndrome, a rare systemic inflammatory disease characterized by early onset granulomatous polyarthritis, uveitis, and dermatitis." (PMID 32823753, 2020). "This fits the concept that the NOD2 mutations in Crohn's disease share a signaling defect, the most pronounced occurs in the frameshift mutation 1007fs." (PMID 32351509, 2020). "In parallel, the NOD2/CARD15 gene is a major susceptibility gene for Crohn’s disease, a chronic, recurrent inflammatory bowel disease (IBD)." (PMID 32899315, 2020). "NOD2 (nucleotide binding oligomerization domain 2) came into the focus since the revolutionary observation that single nucleotide polymorphisms in various genes are related to the risk of Crohn's disease, in particular ileal Crohn's disease." (PMID 32351509, 2020). "The expression of miRNA-320 has been negatively correlated with the expression of nucleotide binding oligomerization domain containing 2 (NOD2), the first gene that was associated which increased susceptibility to Crohn’s disease." (PMID 32858892, 2020). "This strain was sufficient for significantly inducing expression of antimicrobial peptides in vivo through the Crohn’s disease predisposing gene encoding for the nucleotide-binding oligomerization domain, containing protein 2 (NOD2)." (PMID 32210304, 2020). "Nevertheless, NOD2 polymorphism has been linked to the risk of developing other diseases, such as Crohn disease, and even to the outcome of HSCT." (PMID 33552044, 2020). "Mutations in NOD2 are associated with a higher risk of developing chronic inflammatory disorders such as Crohn’s disease, providing a link between the activity of these pathogen sensors and chronic inflammation." (PMID 32487756, 2020). "As the second example, the NOD2 gene is identified by PMR-Egger to be associated with Crohn’s disease (CD; p = 6.1 × 10−19), and, with a slightly less significance, also by CoMM (p = 7.8 × 10−15)." (PMID 32737316, 2020). "Nod2 polymorphism is also a risk factor for Crohn’s disease, and Nod2 and Atg16L1 work cooperatively in bactericidal autophagy." (PMID 31932716, 2020). "In this chromosomal region, NOD2 was identified five years later as the first gene to be associated with susceptibility to Crohn’s disease (CD)." (PMID 32716958, 2020). "The NOD2 (nucleotide-binding oligomerization domain containing protein 2), a first gene locus, has been reported as a risk locus for Crohn’s disease (CD)." (PMID 31412603, 2019). "NOD2 is the strongest associated Crohn's susceptibility gene and Crohn's disease patients who express NOD2 polymorphisms display loss of function for induction of NOD2 effector genes and NOD2/TLR2 specific genes." (PMID 31114588, 2019). "The NOD2 gene, involved in innate immune responses to bacterial peptidoglycan, has been found to be closely associated with Crohn’s Disease (CD), with an Odds Ratio ranging from 3–36." (PMID 30769939, 2019). "The study was conducted among 70 Hungarian males and 72 females with a mean age of 36.2 years, and the results showed that the NOD2 mutations were 29.6% more prominent in patients diagnosed with Crohn’s disease compared to the controls." (PMID 31723489, 2019). "Polymorphisms in NOD2 represent the strongest known genetic risk factors associated with the development of Crohn's disease." (PMID 31114588, 2019).
Crohn disease (continued). "During the beginning of 2001, NOD2 was identified as the first susceptibility gene for Crohn’s disease." (PMID 31723489, 2019). "Three major mutations associated with the NOD2 gene are known to have an influence on Crohn’s disease (SNP8, SNP12, and SNP13)." (PMID 31723489, 2019). "Other studies previously reported and satisfactorily described the involvement of NOD2 rare variants in the genetic Crohn’s disease predisposition." (PMID 30769939, 2019). "Mutations in NOD2 are associated predominantly with Crohn’s Disease and result in a failure to induce NF-κB in response to ligand." (PMID 31131275, 2019). "Nucleotide-binding oligomerization domain 2 (NOD2) is the first gene found to be associated with Crohn's disease, which is frequently mutated in patients with Crohn's disease, occurring in around one-third of the patients." (PMID 31886308, 2019). "Polymorphisms in NOD2 remain the strongest known genetic risk factors in the development of Crohn’s disease." (PMID 29198621, 2019). "In patients with chronic inflammatory diseases, including Crohn’s disease, NOD2 alterations or mutations have been identified." (PMID 31723489, 2019). "NOD2 variants confer the greatest single genetic risk factor for Crohn's disease disease, yet significant gaps remain in our knowledge of how this receptor exerts its effects." (PMID 31379806, 2019). "Three mutations of human NOD2 (R702W, G908R, and L1007insC) are also highly associated with susceptibility to Crohn’s disease in the intestinal tract." (PMID 29872030, 2019). "This was reported to be associated with decreased xenophagy in a manner similar to loss of function of two other well-known Crohn’s Disease associated proteins, Nod2 and XIAP, both of which also positively regulate autophagy." (PMID 31131275, 2019). "There are some SNPs of NOD2 that have been identified as susceptibility loci of Crohn's disease, including 1007 fs, G908R, P268S, and R702W." (PMID 30950247, 2019). "Single nucleotide polymorphisms (SNPs) in the NOD2 gene were the first identified genetic risk factors associated with Crohn’s disease (CD)." (PMID 31632962, 2019). "For example, genetic studies have implicated TLRs in Crohn’s Disease and chronic ulcerative colitis, in addition to the well described role of NOD-2." (PMID 31697716, 2019). "For instance, Crohn's disease patients associated with 1007fs mutation in the NOD2 gene show a much more severe disease phenotype than other Crohn's disease patients, while R702W and G908R mutations lead to increase inflammatory cytokine responses." (PMID 31886308, 2019). "NOD2 mutations are associated with several inflammatory diseases, such as graft versus host disease, Blau syndrome, and Crohn’s disease." (PMID 31723489, 2019). "Inflammatory bowel disease, particularly Crohn’s disease, is the most commonly associated pathology associated with NOD2 signaling." (PMID 31632962, 2019). "Mutational analysis led us to identify the essential domain (residues 200–224) of NLRP12 that is interacting with the Crohn’s disease predisposing NOD2 protein." (PMID 30559449, 2018). "Intensive research conducted in the search for genetic factors underlying the etiopathogenesis of inflammatory bowel disease has resulted in the identification of the CARD15/NOD2 gene, which is associated with increased predisposition to Crohn's disease." (PMID 30648106, 2018). "miRNA-29 downregulates IL-12p40/IL-23 and attenuates Th17 CD4+ T cell responses; however, Crohn’s disease DCs expressing associated NOD2 variants are incapable of inducing miR-29 following NOD2 triggering." (PMID 29515999, 2018). "Collectively, this study not only reaffirms the role of common variation in NOD2 as the primary genetic risk for Crohn’s disease but also defines the role of rare variation in NOD2 in the causation of Crohn’s disease." (PMID 30166421, 2018).
Crohn disease (continued). "In line with this, expression of IL-17 following MDP stimulation is impaired in DCs derived from Crohn’s disease patients with polymorphisms in the NOD2 gene." (PMID 29515999, 2018). "Common genetic variations in NOD2 has been associated with Crohn’s disease and here we investigated the influence of these genetic variations on the anti-Aspergillus host response." (PMID 29980664, 2018). "Mutations in Nod2 are associated with a number of human inflammatory disorders, including Crohn’s disease." (PMID 29552291, 2018). "As in Crohn disease patients with the NOD2 2722G > C variant, patient IB led to an apparent paradox: reduced NF-κB transactivating activity associated with more inflammation." (PMID 29554915, 2018). "Loss of NF-κB signalling results in a failure to up-regulate cytokines in response to NOD2 signalling and this link to NOD2 signalling is thought to be the cause of Crohn’s disease in XIAP deficient patients." (PMID 29743550, 2018). "Here the authors show that a common NOD2 genetic variant associated with Crohn’s disease is associated with reduced risk of disease due to enhanced antifungal activates of monocytes and macrophages." (PMID 29980664, 2018). "NOD1/2 signaling contributes to gastro‐intestinal immunity, and genetic variants in NOD2 are the strongest susceptibility factors to Crohn's disease—one of the two major inflammatory bowel diseases afflicting millions in Europe and North America alone." (PMID 30026309, 2018). "One of them referred as “X” was of particular interest due to the identification of NOD2 variants, including the G908R mutation that has been described in Crohn’s disease." (PMID 29554915, 2018). "First, we again demonstrate that common and rare variation in NOD2 represents the most important genetic risk factor for Crohn’s disease." (PMID 30166421, 2018). "Nucleotide-binding Oligomerization Domain-2 (NOD2) mutations are associated with an increased risk to develop Crohn’s Disease." (PMID 30250234, 2018). "Another noteworthy observation is that VDR was centred by MUC19, MST1, ATG16L1 and NOD2, which synergistically contributed to Crohn's disease risk." (PMID 29441677, 2018). "In 2001, NOD2 was found to be associated with Crohn’s disease and it remains one of the strongest genetic risk factors." (PMID 29515999, 2018). "It has been reported that the production of α-defensins is reduced in Crohn’s disease patients, especially those who have NOD2 gene mutations." (PMID 30558299, 2018). "The large odds ratios indicated a strong risk effect in the MST1, JAK2 and NOD2 gene to Crohn's disease." (PMID 29441677, 2018). "Studies in patients with Crohn’s disease and Nod2-deficient mice showed that intestinal changes in bacterial composition are associated with altered α-defensin expression in the intestinal mucosa." (PMID 28647345, 2017). "Mutations in the leucine-rich region of the NOD2/CARD15 gene are associated with the pathogenesis of several chronic inflammatory diseases of barrier organs including Crohn’s disease, asthma, and Blau syndrome." (PMID 28647345, 2017). "miR-155 was upregulated in Crohn’s disease patients with NOD2 mutations following lipopolysaccharide and Escherichia coli treatment, but the upregulation was substantially reduced upon muramyl dipeptide treatment." (PMID 29263823, 2017). "NOD2 is amongst the most studied of loci underlying Crohn’s disease susceptibility, and there are several protein-coding variants apparently linked to disease." (PMID 28263993, 2017). "These mice carry a known Crohn’s disease-associated ‘knockin’ mutation in the Nod2 locus but also carry a duplication of the 3′ end of the wild-type (WT) Nod2 locus, and herein are designated as Nod2m/m mice." (PMID 29216926, 2017). "The aim of this study was to determine the prevalence of NOD2/CARD15 gene mutations in a group of Moroccan patients with Crohn’s disease and to study its correlation with genotype-phenotypic expression." (PMID 28819537, 2017).
Crohn disease (continued). "There are several susceptibility genes associated with Crohn’s disease, such as nucleotide-binding oligomerization domain-containing protein 2 (NOD2), which is expressed predominantly by Paneth cells in the small intestine." (PMID 28316967, 2017). "The genetic analysis of patients with Crohn’s disease highlighted the presence of NOD2 mutation in 14 patients (13.77%) versus 7 patients (6.53%) in the control group." (PMID 28819537, 2017). "Since its identification in 2001 and its association with Crohn disease (CD), the role of NOD2 in both innate and adaptive immune responses gained increasing interest." (PMID 28253332, 2017). "Genetic variations in NOD1 and NOD2 are associated with increased susceptibility to Crohn's disease." (PMID 29254180, 2017). "NOD2 polymorphisms in patients with Crohn’s disease are associated with decreased intestinal defenses via reduced secretion of antimicrobial proteins and intracellular killing of microbes." (PMID 27908847, 2017). "Certain mutations in the nucleotide-binding oligomerisation domain-containing 2 (NOD2) gene, for example, are associated with an increased risk of the inflammatory bowel disease, Crohn’s disease." (PMID 29216926, 2017). "The association of NOD2 mutations with a number of inflammatory pathologies, including Crohn disease (CD), Graft-versus-host disease (GVHD), and Blau syndrome, highlights its pivotal role in host–pathogen interactions and inflammatory response." (PMID 28253332, 2017). "A growing body of literature links NOD2/CARD15 polymorphisms with a dysregulated innate immune response and susceptibility to diseases, including Crohn’s disease, Blau syndrome, early-onset sarcoidosis, and graft-versus-host disease." (PMID 28647345, 2017). "NOD2 was found to be associated with Crohn's disease 37, ischemic cardiovascular disease 38, Blau syndrome 39, allergic rhinitis 40, and artherosclerosis." (PMID 28960882, 2017). "Known as a major genetic risk factor for Crohn’s disease (CD), NOD2 gene is located on human chromosome 16p21." (PMID 27703457, 2016). "Significantly lower functional activity of the MBL-MASP complex was observed in Crohn’s disease patients carrying the NOD2 variant rs2066844 (R702W) compared to those with the NOD2 wild-type (P < 0.05)." (PMID 27404661, 2016). "NOD2 is central to responses to intracellular pathogens, and SNPs in the NOD2 region have been linked to leprosy and Crohn’s disease." (PMID 27015630, 2016). "Our findings of B cells surrounding granulomas in Crohn’s disease extend previous observations from the 1980s, and more recent ones from pediatric patients with Crohn’s disease with NOD2 gene mutations." (PMID 27468085, 2016). "Nucleotide-binding oligomerization domain-containing protein 2 (NOD2) is a cytoplasmic pattern recognition receptor that is linked to the development of Crohn's disease in humans." (PMID 27790385, 2016). "The NOD2 variant rs2066844 was found in 19 Crohn’s disease patients (heterozygous mutations C_T) with B1 (73.3%), B2 (15.8%) and B3 (10.5%), respectively." (PMID 27404661, 2016). "It should be noted that despite years of intensive research, the mechanism by which single-nucleotide polymorphisms (SNPs) in NOD2 lead to the enhanced inflammation associated with Crohn's disease remains enigmatic." (PMID 27297389, 2016). "Crohn’s disease-associated SNPs like NOD2 (rs2066844, rs2066845, rs2066847) were more common in CD patients than UC patients." (PMID 26732016, 2016). "The genetic association of NOD2/CARD15 with Crohn’s disease has established a critical link between innate immune cells, the intestinal epithelium and development of the disease." (PMID 27404661, 2016). "Crohn’s disease-associated NOD2 polymorphisms exhibit a reduced capacity to activate NF-κβ following muramyl dipeptide stimulation, suggesting that the loss of NOD2 activation promotes Crohn’s disease." (PMID 27404661, 2016).